TSC22D1 (TSC22 domain family member 1)
Description:
Transcriptional repressor. Acts on the C-type natriuretic peptide (CNP) promoter. Acts to promote CASP3-mediated apoptosis. Positively regulates TGF-beta signaling by interacting with SMAD7 which inhibits binding of SMAD7 to TGFBR1, preventing recruitment of SMURF ubiquitin ligases to TGFBR1 and inhibiting SMURF-mediated ubiquitination and degradation of TGFBR1. Contributes to enhancement of TGF-beta signaling by binding to and modulating the transcription activator activity of SMAD4. Promotes TGF-beta-induced transcription of COL1A2; via its interaction with TFE3 at E-boxes in the gene proximal promoter (By similarity). Plays a role in the repression of hematopoietic precursor cell growth (By similarity). Promotes IL2 deprivation-induced apoptosis in T-lymphocytes, via repression of TSC22D3/GILZ transcription and activation of the caspase cascade. [Isoform 1]: May act to negatively regulate TGFB3 signaling and thereby inhibit cell death in mammary gland cells. [Isoform 2]: Positively regulates cell death in response to TGFB3 during mammary gland involution.
Synonyms: HUCEP-2; TGFB1I4; TSC22; MGC17597; Ptg-2
Tractability: Antibody: UniProt places it where antibodies can reach, with high confidence; its Gene Ontology location is reachable by antibodies, with high confidence. PROTAC: ubiquitination databases record sites on it; its protein half-life has been measured.
Gene: Protein-coding gene on chromosome 13 (44,432,143 to 44,577,316, reverse strand). Ensembl gene ENSG00000102804.
Subcellular location: Cytoplasm; Nucleus; Cell membrane; Cytoplasm (Isoform 1); Mitochondrion; Cytoplasm (Isoform 2); Cytoplasm (Isoform 5)
Subcellular location (Human Protein Atlas): Nuclear bodies; Nucleoplasm
Pathways (Reactome):
Developmental Biology: POU5F1 (OCT4), SOX2, NANOG repress genes related to differentiation
Gene Ontology:
Molecular function: identical protein binding; protein binding; transcription coactivator activity
Biological process: positive regulation of apoptotic process; positive regulation of transforming growth factor beta receptor signaling pathway; negative regulation of apoptotic process; negative regulation of hematopoietic stem cell proliferation; negative regulation of programmed cell death; positive regulation of cell population proliferation; positive regulation of programmed cell death; transcription by RNA polymerase II; positive regulation of DNA-templated transcription; regulation of transcription by RNA polymerase II
Cellular component: cytoplasm; mitochondrion; nucleus; plasma membrane; cytosol
Genetic constraint (gnomAD): Loss-of-function variants: 9 observed, 78.96 expected, observed/expected ratio (o/e) 0.11, 90% interval 0.068 to 0.2. The upper end of that interval is the gene's LOEUF score, 0.2, which puts it in group 1 of 6, group 1 being the genes least tolerant of losing a copy. Missense variants: 1,427 observed, 1,366.8 expected, observed/expected ratio (o/e) 1.04, 90% interval 1 to 1.09. Synonymous variants: 586 observed, 515.42 expected, observed/expected ratio (o/e) 1.14, 90% interval 1.06 to 1.22.
Homologues: Orthologues: chimpanzee TSC22D1 (99% identical), macaque TSC22D1 (97% identical), dog TSC22D1 (90% identical), guinea pig TSC22D1 (88% identical), mouse Tsc22d1 (86% identical), rat Tsc22d1 (75% identical), zebrafish tsc22d1 (32% identical), Drosophila melanogaster bun (16% identical), Caenorhabditis elegans Y48C3A.12 (13% identical), Caenorhabditis elegans tsct-1 (8% identical). Paralogues in human: TSC22D2 (21% identical), TSC22D4 (13% identical), TSC22D3 (9% identical).
Diseases named in the same sentence as TSC22D1 in open-access papers:
TSC22D1 is named in the same sentence as 45 diseases in open-access papers, as found by Europe PMC text mining. Sharing a sentence is not in itself a finding about the gene and the disease. The quoted sentences say what the papers report.
cervical carcinoma (6 papers, 2012 to 2026). A carcinoma arising from either the exocervical squamous epithelium or the endocervical glandular epithelium. "A rescue experiment was carried out to see if TSC22D1 was involved in the consequences of MEX3D-mediated carcinogenesis in cervical cancer cells." (PMID 35513372, 2022). "TSC22D1 was found to be a critical inhibitory factor in the carcinogenesis of cervical cell, and TSC22D1 is essential for reducing the tumorigenic potential of cervical cancer cells induced by MEX3D." (PMID 35513372, 2022). "The findings revealed that MEX3D is upregulated by HPV16 E7 and has a crucial oncogenic in cervical cancer development via sponging TSC22D1 for destabilizing its mRNA levels." (PMID 35513372, 2022). "The data indicated that MEX3D was associated with TSC22 domain family protein 1 (TSC22D1) RNA levels and that TSC22D1 knockdown could reverse MEX3D knockdown-induced tumorigenesis in cervical cancer cells." (PMID 35513372, 2022). "The mechanism of TSC22D1 in cervical cancer, however, is unknown." (PMID 35513372, 2022). "TSC22D1 is a member of the TSC22D family, is downregulated in glioblastoma, salivary gland, prostate, and cervical cancers." (PMID 41141930, 2025). "The current study presented a theoretical basis for using this target in the management of patients with cervical cancer and identified a new post-transcriptional mechanism involving MEX3D-mediated TSC22D1 transcript destabilization." (PMID 35513372, 2022). "Given that TSC22D1 is a key MEX3D downstream effector, the current study characterized the TSC22D1 functional role in tumorigenesis of cervical cancer." (PMID 35513372, 2022).
Obesity (4 papers, 2016 to 2025). Accumulation of substantial excess body fat. "These included IL1R1 (hypermethylated among lean), FMNL2 (hypermethylated in obesity) in OVAT and TSC22D1 (hypermethylated in obesity) in SAT." (PMID 41225618, 2025). "Further, we investigated in more detail selected DMRs in TSC22D1, HAS2, GCC1, NCKIPSD from SAT, all being hypermethylated in individuals with obesity and BCCIP, IL1R1 (hypermethylated in lean) and FMNL2 (hypermethylated in individuals with obesity) from OVAT." (PMID 41225618, 2025).
gastric cancer (2 papers, 2012 to 2025). A primary or metastatic malignant neoplasm involving the stomach. "As an additional tissue-level validation, TSC22D1 mRNA expression was measured in primary gastric cancer tissues." (PMID 41472023, 2025). "The regulatory axis between YTHDF1 and TSC22D1 highlights a previously unrecognized mechanism through which EBV promotes gastric cancer progression." (PMID 41472023, 2025). "m6A RNA immunoprecipitation sequencing (MeRIP-seq) revealed a significant reduction in m6A methylation of TSC22D1 in EBV-infected gastric cancer cells (AGS-EBV) compared with EBV-negative cells (AGS)." (PMID 41472023, 2025). "In this study, we investigated how EBV infection alters the m6A methylation pattern in gastric cancer cells and examined its impact on TSC22D1 mRNA stability through interaction with the m6A reader protein YTHDF1." (PMID 41472023, 2025). "In conclusion, our study reveals a novel epitranscriptomic mechanism through which EBV promotes gastric cancer, involving miRNA-mediated suppression of YTHDF1 and selective hypomethylation of TSC22D1 mRNA." (PMID 41472023, 2025).
thyroid cancer (2 papers, 2022 to 2025). "The study demonstrates that DUSP6 and TSC22D1 are significantly upregulated in BRAFV600E mutant thyroid cancer and play an important role in the escape mechanism of tumor cells from OIS." (PMID 40650680, 2025). "Univariate Cox regression analysis was further applied to assess the prognostic value of DEFRGs, and we found that 4 DEFRGs (APOE, P = 0.004; TSC22D1, P = 0.025; TIMP1, P = 0.029; HTRA3, P = 0.007) may act as independent factors for overall survival of thyroid cancer." (PMID 36387901, 2022).
colon cancer (1 paper, 2016). "Co-expression analysis revealed that ACSL1 was coexpressed with MYBPH, PTPRE, PFKFB3, SOCS3 in colon cancer and with LRRFIP1, TSC22D1 in lung cancer." (PMID 27171439, 2016).
diabetes (1 paper, 2025). "Our study provides critical insights into the role of TSC22D1 in beta cell function, highlighting its potential as a therapeutic target to enhance insulin secretion in diabetes." (PMID 40679946, 2025). "Overall, our findings indicate that TSC22D1 plays a significant role in regulating beta cell function at multiple levels, with potential implications for metabolic diseases, such as diabetes." (PMID 40679946, 2025).
endothelial dysfunction (1 paper, 2025). In vascular diseases, endothelial dysfunction is a systemic pathological state of the endothelium (the inner lining of blood vessels) and can be broadly defined as an imbalance between vasodilating and vasoconstricting substances produced by (or acting on) the endothelium. "TSC22D1 emerges as a pivotal transcriptional regulator with context-dependent roles in cell fate, potentially contributing to both GERD and IS through pathways involving cellular senescence and endothelial dysfunction." (PMID 41305834, 2025).
gastric tumors (1 paper, 2025). "Second, YTHDF1 and TSC22D1 may serve as molecular biomarkers for stratifying EBV-positive versus EBV-negative gastric tumors or for predicting therapeutic response." (PMID 41472023, 2025).
Hyperglycemia (1 paper, 2025). An increased concentration of glucose in the blood. "We can answer this question by suggesting that perhaps TSC22D1 simply acts within a feedback loop to fine‐tune insulin secretion, or it might also act as an inhibitor of insulin secretion upon prolonged hyperglycemia to prevent beta cell exhaustion." (PMID 40679946, 2025).
liver cancer (1 paper, 2013). An epithelial or non-epithelial malignant neoplasm that arises from the liver. "Furthermore, TSC22D1 was recently found to antagonize Ras/Raf signaling, thereby exerting anti-tumourigenic effects in a Ras/Raf-dependent liver cancer model, and TSC22D1 abrogated TGF-beta-induced growth rates in intestinal epithelial cells." (PMID 23307490, 2013).
lung carcinoma (1 paper, 2016). "As for lung cancer, ACSL1 was coexpressed with leucine rich repeat (in FLII) interacting protein 1 (LRRFIP1) and TSC22 domain family member 1 (TSC22D1)." (PMID 27171439, 2016).
osteosarcoma (1 paper, 2024). A usually aggressive malignant bone-forming mesenchymal neoplasm, predominantly affecting adolescents and young adults. "The best-characterized member of this protein family is TSC22D1, which possesses a tumor-suppressor function, and TGF-β1-stimulated clone 22 (TSC-22/TSC22D1) was first identified as a target gene of TGF-β1 in mouse osteosarcoma cells." (PMID 38612684, 2024).
ovary cancer (1 paper, 2023). "An exemplary analysis of the two PRDM15 co-dependency genes MNT and RALGDs revealed that it is correlated with MNT in both ovary cancer cell lines and blood cancer cell lines and negatively correlated with TSC22D1 in blood cancer cell lines." (PMID 36674842, 2023).
pulmonary fibrosis (1 paper, 2022). Chronic progressive interstitial lung disorder characterized by the replacement of the lung tissue by connective tissue, leading to progressive dyspnea, respiratory failure, or right heart failure. "TSC22D1 (TSC22 domain family, member 1) and MXI1 (MAX interactor 1) are also associated with pulmonary fibrosis in some transcriptomic, miRNomic, and methylation array data." (PMID 35980387, 2022).
tonsillar carcinoma (1 paper, 2022). "In order to find the specific genes of BOT carcinoma, we screened and identified the differential genes of BOT carcinoma, oral tongue carcinoma, and tonsillar carcinoma in TCGA open datasets, and finally picked out TSC22D1 as the specific gene of BOT carcinoma." (PMID 36465343, 2022).
tumor (21 papers, 2008 to 2025). "Tsc22d1 encodes a leucine zipper transcription factor that plays a role in tumor suppression and Gadd45b encodes a protein involved in the regulation of growth and apoptosis." (PMID 29706024, 2018). "While one study has reported TSC22D1 as a putative tumor suppressor, another study has demonstrated antiapoptotic functions associated with TSC22D1." (PMID 27340651, 2013). "Therapeutic strategies aimed at restoring YTHDF1 function or reducing TSC22D1 expression may suppress tumor growth, particularly in EBV-associated gastric cancer (EBVaGC), which currently lacks targeted therapies." (PMID 41472023, 2025). "TSC22D1, also called transforming growth factor-β-stimulated clone-22, was reported to play a tumor suppressor role in tumors." (PMID 37237254, 2023). "The second group, whose expression peaked at the early-MM disease stage, consisted of Il5ra, a cytokine receptor, Mgmt, a methyltransferase crucial for genome stability, and Tsc22d1, a pro-apoptotic tumour suppressor." (PMID 34732728, 2021). "In contrast, Pe1 EC markers, including SLCO1A2, ANXA3, and TSC22D1, were enriched in leading edge and infiltrating tumor regions." (PMID 34228647, 2021). "Reciprocal regulation of the putative tumor suppressor gene Tsc22d1, which leads to the suppression of Gadd45b and that of other cancer‐associated target genes (Iida, Anna, Gaskin, Walker & Devereux, 2007), may also account for the lower rate of tumor progression in RedTg livers." (PMID 29706024, 2018). "In addition, DCBLD2, CASP7, TSC22D1, ANXA7, PRKAR2A, ZMYND11, and PAK2 have been reported to be tightly linked to tumor malignancy in previous studies." (PMID 35513372, 2022). "MEX3D played a vital role by reducing TSC22D1 mRNA stability in apoptosis and tumor growth." (PMID 35513372, 2022). "In Omy03, we found the domain family protein 1 (TSC22D1) gene that participates as an early immune response molecule and that modulates the TGF-beta dependent signaling pathway, a tumor suppressor in cells, and induces cellular apoptosis and senescence." (PMID 36672855, 2022). "Tumor ECs in early-stage tumors strongly expressed PLVAP, GSN, and TSC22D1, which are relevant to the development and cell-fate commitment of ECs15." (PMID 34764257, 2021). "Its correlations with key immune-related genes, including TRBV, CD40, and TSC22D1, suggest that PRSS2 may be involved in tumor immune regulation, potentially contributing to improved clinical outcomes." (PMID 41141930, 2025).
cancer (13 papers, 1998 to 2024). A tumor composed of atypical neoplastic, often pleomorphic cells that invade other tissues. "The data indicated that the MEX3D/TSC22D1 complex regulated cancer-associated functions as a consequence of HPV16 E7 overexpression." (PMID 35513372, 2022). "CHST2, SPACA6, and TSC22D1 had lower methylation levels in cancer tissues than Riplet and GNB4, in which CHST2 and TSC22D1 had higher methylation levels in normal tissues." (PMID 38154055, 2024). "Human TSC22D1 is a candidate suppressor, and its expression has been confirmed in various cancer types, such as malignancies of the salivary glands, prostate, and brain." (PMID 35513372, 2022). "TSC22D domain family genes, including TSC22D1-4, play a principal role in cancer progression." (PMID 37237254, 2023). "TSC22D1 mRNA expression was also high in other types of cancer." (PMID 27340651, 2013). "Interestingly, higher DNA copy number of TSC22D1 was observed in stages IV/IVA indicating towards a potential role of TSC22 domain family in enabling dissemination of late-stage carcinoma cells." (PMID 27340651, 2013). "The prototypical TSC-22 protein, TSC22D1-001, may act as a transcriptional regulator and repress cancer cell proliferation, particularly for blood lineages." (PMID 26323255, 2015).
blood cancer (1 paper, 2023). "Among them, HPRT1, TSC22D1, and COX16 have significantly correlated dependence profiles (p < 0.05) with PRDM15 in lymphocyte or blood cancer cell lines from these pathways." (PMID 36674842, 2023).
TSC22D1 also shares sentences with these, for which no sentence is quoted: breast carcinoma (3 papers); brain tumor (2); Myocardial fibrosis (2); myocardial infarction (2); astrocytomas (1); B cell lymphoma (1); cardiomyopathy (1); cervical tumor (1); colorectal cancer (1); glioblastoma (1); heart failure (1); hypertrophy (1); infarction (1); infection (1); Intellectual disability (1); left ventricular hypertrophy (1); leukemia (1); lung (1); melasma (1); metabolic disease (1); non-small cell carcinoma (1); prostate carcinoma (1); rheumatoid arthritis (1); salivary gland cancer (1); salivary gland tumors (1); Stroke (1); type 2 Diabetes (1).